FGFR1 (fibroblast growth factor receptor 1)
Diseases named in the same sentence as FGFR1 in open-access papers (continued):
Sharing a sentence is not in itself a finding about the gene and the disease.
soft tissue sarcoma (7 papers, 2011 to 2025). A malignant neoplasm arising from muscle tissue, adipose tissue, blood vessels, fibrous tissue, or other supportive tissues excluding the bones. "In addition, FGFR1 has been shown to represent a driver gene in multiple soft tissue sarcoma subtypes characterized by its amplification/overexpression, thus representing a potential therapeutic target in these tumors." (PMID 30443492, 2018). "For this purpose we interrogated SNF5, FGFR1 and FGFR2 mRNA expression in a total of 991 human primary soft tissue sarcomas from publically available Affymetrix datasets and including 10 rhabdoid tumors." (PMID 24204904, 2013).
Stroke (7 papers, 2020 to 2025). Sudden impairment of blood flow to a part of the brain due to occlusion or rupture of an artery to the brain. "Some of the DECs we identified are encoded by genes such as Phactr1, Fgfr1, and others that have been shown to be associated with stroke." (PMID 41226594, 2025). "Western blot analysis confirmed increased post-stroke cerebral angiogenesis in HMW-HA treated mice, as presented by higher expression of VEGFR, VEGF2, FGF2, and FGFR1 3 days following MCAO." (PMID 34992208, 2022). "Stroke induced a significant increase in VEGFA, VEGFR2, FGF2, and FGFR1 expression 1–3 days after MCAO." (PMID 34992208, 2022). "In conclusion, nmFGF1 enhanced angiogenesis in mice following stroke and OGD-induced HBMECs through S1P1 pathway regulation mediated via FGFR1 activation." (PMID 32194396, 2020).
hearing loss (6 papers, 2017 to 2024). "In a clinical sense, recognizing those IHH genes and associated phenotypes may improve our diagnostic capabilities by enabling us to prioritize the screening of particular gene(s) such as synkinesia (ANOS1), dental agenesis (FGF8/FGFR1) and hearing loss (CHD7)." (PMID 29280744, 2017). "Moreover, FGFR1 protein we found enriched in CDsEVs, which may be involved in HC survival, provides a new study target of HC protection and may help discover new therapeutic treatment for hearing loss." (PMID 39497619, 2024). "DUSP6 (Dual Specificity Phosphatase 6; chr 12q21.33) and SPRY4 (Sprouty RTK Signaling Antagonist 4; chr 5q31.1) are repressors of the FGF8/FGFR1-activated MAPK cascade and pathogenic variants were found in patients with either normosmic CHH and KS together with hearing loss." (PMID 34502334, 2021).
intrahepatic cholangiocarcinoma (6 papers, 2017 to 2025). A carcinoma that arises from the intrahepatic bile duct epithelium in any site of the intrahepatic biliary tree. "Aberrations in FGFR1–4 are found in 5–10% of human cancers, with increased frequency (10–30%) in urothelial cancer and intrahepatic cholangiocarcinoma." (PMID 38098111, 2023). "We present the case of a 69-year-old Caucasian patient with advanced intrahepatic cholangiocarcinoma who received the therapy with selective oral inhibitor of fibroblast growth factor receptor 1, 2, and 3 pemigatinib after multiple previous chemotherapies." (PMID 38098111, 2023). "The results of phase 2 study FIGHT-202 and FDA approval of pemigatinib in 2020 as the first FGFR1–3 inhibitor in the treatment of advanced intrahepatic cholangiocarcinoma with FGFR2 fusions or arrangements have led to improvements in the therapeutic strategies of this tumor entity." (PMID 38098111, 2023).
multiple myeloma (6 papers, 2014 to 2023). "Dovitinib targets FGFR1/2/3 and is under clinical trial investigation as an anti-tumor drug, with FGFR1 chromosomal translocation associated with 8p11 myeloproliferative syndrome, and FGFR3 is implicated in multiple myeloma and peripheral T-cell lymphoma." (PMID 38002949, 2023). "Oncogenic fusions of FGFR1 with various fusion partners were described in myeloid proliferative neoplasms, and overexpression and mutations of FGFR3 are common in multiple myeloma." (PMID 30755670, 2019). "In contrast, the FGFR1-equivalent substitution in FGFR3 (V555M) is highly likely to occur and was previously identified in the context of a cancer cell line (multiple myeloma KMS-11) dependent on an FGFR3 Y373C driver mutation." (PMID 26097890, 2015). "Thus, the overexpression of FGFR1, CCR2, and SGK1 may explain the low sensitivity of multiple myeloma (MM) cells to bortezomib and ixazomib." (PMID 33406639, 2021).
multiple sclerosis (6 papers, 2016 to 2024). A progressive autoimmune disorder affecting the central nervous system resulting in demyelination. "The results are similar to those seen in neurological diseases such as Alzheimer’s disease (AD) and multiple sclerosis (MS) where increased FGFR1 staining in white matter of AD and MS patients has been reported." (PMID 38638441, 2024). "Deletion of Fgfr1 or Fgfr2 in oligodendrocytes was shown to inhibit myelin and axon degeneration in mouse models of experimental autoimmune encephalitis (a multiple sclerosis model)." (PMID 38638441, 2024). "Conversely, skewing signaling to favor FGFR1 also prevents the ability of FGF2 to induce MMPs implicated in blood-brain barrier damage and leucocyte recruitment in multiple sclerosis and other neurological diseases." (PMID 31856924, 2019). "In addition, FGF2/FGFR1 signaling could regulate inflammation of hippocampus to exert a positive effect on some neurodegenerative diseases such as Parkinson’s disease, Alzheimer’s disease, multiple sclerosis, and traumatic brain injury." (PMID 30210273, 2018). "FGF-2 and Anosmin-1, which are markers for the level of inflammation of multiple sclerosis lesions, participate in oligodendrocyte precursor cell migration via FGF receptor 1 (FGFR1)." (PMID 27642302, 2016).
osteoarthritis (6 papers, 2016 to 2024). A noninflammatory degenerative joint disease occurring chiefly in older persons, characterized by degeneration of the articular cartilage, hypertrophy of bone at the margins and changes in the synovial membrane. "In models of abnormal dental occlusion and age‐associated spontaneous osteoarthritis, the loss of FGFR1 inhibits the development of osteoarthritis by promoting autophagic activity." (PMID 33949768, 2021). "Studies on FGFR1 inhibitors have shown that they can effectively protect articular cartilage from the effects of osteoarthritis." (PMID 39684926, 2024). "The upregulated amount of FGFR1 (fibroblast growth factor receptors) signalling suggesting the progression of degenerative cartilage that commonly seen in osteoarthritis (OA) patients." (PMID 35836973, 2022). "Acknowledging the potential of FGFR1-bound EVs, the authors are interested in studying further regarding this modality so that it can provide better prospects in the management of osteoarthritis." (PMID 35836973, 2022). "Liu and colleagues proposed that TNFSF10 overexpression probably stimulated proliferation and inflammation and inhibited apoptosis by regulating the miR-376-3p/FGFR1 axis in osteoarthritis." (PMID 35151359, 2022). "The aim of this review is to evaluate the potential use of fibroblast growth factor receptor 1-bound extracellular vesicle as novel therapy for osteoarthritis." (PMID 35836973, 2022). "The attenuated degradation of articular cartilage by cartilage-specific deletion of fibroblast growth factor receptor 1 (FGFR1) in adult mice suggests that FGFR1 is a potential target for treating osteoarthritis (OA)." (PMID 27041213, 2016). "It results to the point that the novel usage of FGFR1-bound EV-derived MSC could be beneficial in the treatment of osteoarthritis by preventing ligation of FGF1 to the natural FGFR1." (PMID 35836973, 2022). "S100B could participate in the FGFR1-mediated inflammatory response in osteoarthritis." (PMID 34250093, 2021).
osteoporosis (6 papers, 2011 to 2024). A condition of reduced bone mass, with decreased cortical thickness and a decrease in the number and size of the trabeculae of cancellous bone (but normal chemical composition), resulting in increased fracture incidence. "FGF23 signals via a complex of anFGF receptor (FGFR1(IIIc)) and Klotho; mice with a loss-of-functionmutation in Klotho develop osteoporosis amongst otherabnormalities, and modest evidence of association of Klotho withBMD has been reported in several studies." (PMID 21533022, 2011). "Despite numerous investigations on the influence of fibroblast growth factor 23 (FGF23), α‐Klotho and FGF receptor‐1 (FGFR1) on osteoporosis (OP), there is no clear consensus." (PMID 39054573, 2024). "Our findings revealed the critical role of the lncRNA TUG1/miR‐34a/FGFR1 axis in FSS‐regulated osteoblast proliferation and apoptosis and may establish potential therapeutic strategies against osteoporosis." (PMID 34350720, 2021). "Taken together, our study revealed the key role of the lncRNA TUG1/miR‐34a/FGFR1 axis in FSS‐regulated osteoblast proliferation and apoptosis and may provide potential therapeutic targets for osteoporosis." (PMID 34350720, 2021). "Therefore, our findings uncovered the role of the lncRNA TUG1/miR‐34a/FGFR1 axis in FSS‐regulated osteoblast proliferation and apoptosis and may provide promising therapeutic strategies for osteoporosis." (PMID 34350720, 2021).
papillary thyroid carcinoma (6 papers, 2015 to 2025). "For instance, Circ-RAPGEF5 acts as a tumor promoter in papillary thyroid carcinoma by competitively binding miR-198, which represses FGFR1." (PMID 37705041, 2023). "Using western blot and SYBR Green Real time PCR we investigated 77 thyroid tissues including 19 goiter tissues, 11 follicular adenomas, 16 follicular carcinomas, 15 papillary thyroid carcinomas, and 16 undifferentiated thyroid carcinomas for total expression of PKM2, LDHA and FGFR1." (PMID 25880801, 2015).
pheochromocytoma (6 papers, 2018 to 2024). "Compound pheochromocytomas, which include neuroblastic components, are rare and have been linked to shared genetic mutations, such as alterations in the FGFR1 gene." (PMID 39606041, 2024). "Including a subsequent analysis of a larger cohort, activating FGFR1 mutations were detected in three of 80 sporadic pheochromocytomas (3.8%)." (PMID 29159601, 2018). "Besides RET and HRAS, FGFR1 is only the third protooncogene found to be recurrently mutated in pheochromocytomas." (PMID 29159601, 2018). "The results advance our biological understanding of pheochromocytoma and suggest that somatic FGFR1 activation is an important event in a subset of sporadic pheochromocytomas." (PMID 29159601, 2018). "Similarly to HEK293 cells, mem-opto-FGFR1-transfected pheochromocytoma cells exhibited increased pERK levels, as indicated by intense pERK immunolabeling in the cytoplasm (Figure 4A2/A6,G)." (PMID 30875802, 2019).
cardiac hypertrophy (5 papers, 2017 to 2025). "To obtain further insight into potential FGFR-mediated signalling mechanisms in TAC-induced cardiac hypertrophy, we investigated mRNA expression of Fgfr1, Fgfr3 and Fgfr4 in WT, VDRΔ/Δ, Fgf23−/−/VDRΔ/Δ, and Klotho−/−/VDRΔ/Δ mice, 4 weeks after TAC." (PMID 28900153, 2017). "FGF-2 was reported to induce cardiac hypertrophy through activation of FGF receptor 1 (FGFR1)." (PMID 29776409, 2018). "For example, presumably through activation of FGFR1, the paracrine factor FGF2 promotes cardiac hypertrophy under conditions of excess catecholamine stimulation and renin-angiotensin system activation." (PMID 35513431, 2022).
Cirrhosis (5 papers, 2008 to 2023). A chronic disorder of the liver in which liver tissue becomes scarred and is partially replaced by regenerative nodules and fibrotic tissue resulting in loss of liver function. "A recent study also showed that the expression levels of FGFR1 were enhanced in adults suffering from cirrhosis." (PMID 38137441, 2023). "FGFR1 overexpression showed a significant association with HCV (p < 0.0001) and cirrhosis (p < 0.0001)." (PMID 35683481, 2022). "We studied the expression levels of FGFR1 in liver from normal and cirrhosis patients by immunostaining and qPCR." (PMID 24848261, 2014). "The clinicopathological analyses were performed for FGFR1, FGFR2, FGFR3 and FGFR4 against age, sex, grade stages, tumor stages, HCV, AFP, cirrhosis, vascular invasion, and cell type (atypical, dysplastic/polygonal, neoplastic) using different statistical approaches." (PMID 35683481, 2022). "Interestingly, a consistent pattern of FGFR1 and FGFR2 was observed in HCV-induced HCC cases, with a downregulation in FGFR1 (p < 0.028) and an upregulation of FGFR2 (p < 0.006) and cirrhosis (p < 0.02)." (PMID 35683481, 2022).
cleft palate (5 papers, 2015 to 2022). Cleft palate is a fissure type embryopathy that affects the soft and hard palate to varying degrees. "A plausible candidate, fibroblast growth factor receptor 1 (FGFR1), is expressed in the frontal epithelia before shelf elevation, and FGFR1 mutations are often associated with cleft palate." (PMID 30708991, 2019). "Previous genetic screening demonstrates that the mutations of Fgfr1 and Fgfr3 are also associated with human cleft palate." (PMID 26332583, 2015).
COVID-19 (5 papers, 2022 to 2026). A disease caused by infection with severe acute respiratory syndrome coronavirus 2. "Endothelial cell population proportions are significantly altered in COVID-19 livers, with the emergence of a large population of FGFR1 and AKAP12-positive cells that may contribute to angiogenesis and promote fibrosis." (PMID 40087773, 2025). "Further studies are also needed to assess whether therapies targeting against fibroblast activation, such as inhibitors of FGFR1 or STAT3, may potentially benefit severely ill COVID-19 patients at risk for or with cardiac microthrombi." (PMID 34905515, 2022). "In either case, our overall findings show the possibility that small molecule inhibition of proteins encoded by fibroblast regulator genes (e.g., FGFR1, STAT3) may be a novel approach to the clinical management of COVID-19 cases, be it in the acute or postacute phase of critical illness." (PMID 34905515, 2022). "In a murine model of severe COVID-19, inhibitors of NAE1 and FGFR1 significantly decreased viral load and lung pathology." (PMID 41585476, 2026). "The ‘prevalent’ ‘candidate genes’ (ADAM10, ADAM17, AKT1, CTNNB1, ESR1, FGFR1, PIK3CA) might have the most prominent pathophysiological relevance in COVID-19." (PMID 36229517, 2022).
dyslipidemia (5 papers, 2017 to 2025). "Our findings suggest that FGF21D2D3 is a more potent and effective protein than FGF21WT for treating DCM through improving dyslipidemia and directly inhibiting oxidative stress via FGFR1–AMPK activation in T2D." (PMID 40724827, 2025). "Therefore, our data indicate that FGF21D2D3 is a better substitute for FGF21WT in treating DCM by improving dyslipidemia and directly suppressing oxidative stress via FGFR1–AMPK activation in T2D." (PMID 40724827, 2025). "This review will discuss FGF21-mediated FGFR1/β-KL signaling pathways in the liver, adipose, and cardiovascular systems, as well as how this signaling is involved in the interplay of these organs during the metabolic syndrome." (PMID 35983184, 2022). "Furthermore, the clinical implications and therapeutic strategies for preventing metabolic syndrome and its complications by targeting FGFR1/β-KL are also discussed." (PMID 35983184, 2022).
encephalocraniocutaneous lipomatosis (5 papers, 2020 to 2025). A rare neoplastic syndrome characterized by the presence of unilateral lipomas of the cranium, face and neck, and ipsilateral cerebral malformations. "Interestingly, mosaic activating variants in FGFR1 have been reported to cause encephalocraniocutaneous lipomatosis (ECCL; MIM 613001), a neurocutaneous condition characterized by ocular anomalies, skin lesions, and central nervous system anomalies." (PMID 38265560, 2024). "FGFR1 N546K and K656E oncogenic variants have been reported in postzygotic mosaicism as the genetic cause of a rare neurocutaneous condition known as Encephalocraniocutaneous lipomatosis (ECCL); however neither variant has so far been reported in the germline, suggesting embryonic lethality." (PMID 41174249, 2025).
ependymoma (5 papers, 2015 to 2025). A WHO grade II, slow growing tumor of children and young adults, usually located intraventricularly. "Tumors with high expression of both FGFR3 and FGFR1 were associated with poor clinical prognosis in ependymoma, suggesting that aggressive supratentorial ependymomas may benefit from treatment regimens based on FGFR inhibition." (PMID 28468611, 2017). "Our results demonstrate that moderate-to-strong FGFR3 and/or FGFR1 immunostaining was detectable in most of the supratentorial ependymomas." (PMID 28468611, 2017). "In ependymomas, increased FGFR3 or FGFR1 expression was associated with high tumor grade, cerebral location, young patient age, and poor prognosis." (PMID 28468611, 2017). "However, one study has shown that FGFR1 and FGFR3 IIIc splice variants are the dominant expressed isoforms in ependymoma." (PMID 37130917, 2023). "Among ependymomas, marked (moderate-to-strong) immunostaining for FGFR1, FGFR3, or both proteins occurred more frequently in cerebral than in non-cerebral tumors (76, 32, and 19% in cerebral, cerebellar, and spinal tumors, respectively, p < 0.001, Fisher’s exact test)." (PMID 28468611, 2017). "However, FGFR inhibition might be a suitable treatment option for ependymomas with moderate-to-strong FGFR3 or FGFR3 + FGFR1 expression, as these patients had poor prognosis and we are currently lacking efficient regimens for their treatment." (PMID 28468611, 2017). "Co-expression of FGFR1/3 with FGFs including FGF1, FGF2 and FGF9 has been identified in specific molecular subtypes and cell sub-populations of ependymoma." (PMID 37130917, 2023). "Ependymoma cases that co-expressed moderate-to-strong levels of both FGFR3 and FGFR1 had significantly lower survival rates." (PMID 28468611, 2017). "In ependymoma, high FGFR1 and FGFR3 expression has been associated with high tumour grade and poor prognosis, in the absence of FGFR1 or FGFR3 mutation." (PMID 37130917, 2023). "Further studies are warranted to evaluate whether ependymoma patients with high FGFR3 and/or FGFR1 expression could benefit from treatment with FGFR inhibitor based therapeutic approaches currently under evaluation in clinical trials." (PMID 28468611, 2017). "Elevated FGFR3 and FGFR1 protein expression is common in aggressive ependymomas but likely not driven by genetic alterations." (PMID 28468611, 2017).
head and neck cancer (5 papers, 2016 to 2025). A primary or metastatic malignant neoplasm affecting the head and neck. "Notably, FGFR TKIs augmented the antitumor effect of FGFR1-reactive T cells against human head and neck cancers." (PMID 40547805, 2025). "FGFR1 fusions were characteristic of head and neck cancer (0.3%)." (PMID 37537783, 2023).
heart failure (5 papers, 2013 to 2025). Inability of the heart to pump blood at an adequate rate to meet tissue metabolic requirements. "Fgfr1, which plays an important role in organ fibrosis, is also up-regulated in arterial ECs during heart failure." (PMID 40772900, 2025). "A further study revealed that the expression of fibroblast growth factor receptor 1 (FGFR1) and FGF21 was opposite in heart failure." (PMID 41173187, 2025). "Interestingly, chronic overexpression of a constitutively activated FGFR1 in cardiomyocytes (CM-caFGFR1) resulted in significant myocardial hypertrophy, pathological remodeling (myocyte disarray and fibrosis), reduced cardiomyocyte relaxation and potential long term diastolic heart failure." (PMID 36211556, 2022).